CXCR4 (C-X-C motif chemokine receptor 4)
Diseases named in the same sentence as CXCR4 in open-access papers (continued):
Sharing a sentence is not in itself a finding about the gene and the disease.
cancer (continued). "Staining of primary cancers revealed significant frequencies of CXCR4+ samples in cancers of the kidney, lung, and pancreas." (PMID 29088715, 2017). "Chemokines and their receptors contribute to cancer metastasis, particularly stromal cell-derived factor-1α and its receptor, CXCR4." (PMID 28969005, 2017). "As part of the initial studies in a project whose goal was to quantify CXCR4 expression on cancers non-invasively, we examined CXCR4 expression in cancer samples by immunohistochemistry using a validated anti-CXCR4 antibody." (PMID 29088715, 2017). "Then we can draw that TAMs in malignant tumors tend to M2 subtype possibly through CXCL12/CXCR4/JAK2/STAT3 signaling pathway." (PMID 28630636, 2017). "Actin polymerization, or cytoskeletal reorganization, is a surrogate marker of cancer cell migration and metastatic potential, induced by the interaction of CXCR4 with CXCL12." (PMID 28526063, 2017). "In a corollary finding, CXCR4 has been well-characterized as a marker to monitor radiation resistance in cancer stem cells." (PMID 29068423, 2017). "There are currently multiple CXCR4-targeting agents in clinical development for cancer, including small molecule antagonists, peptide agonists and antagonists, and anti-CXCR4 mAbs, many of which are being evaluated in combination with immunotherapy." (PMID 29212254, 2017). "At the invading front of pancreatic tumors, a distinct subpopulation of CD133+CXCR4+ cancer stem cells determines the metastatic phenotype of individual tumors." (PMID 27974675, 2017). "Consistently, silencing CXCR4 has been shown to inhibit cancer migration, including migration in PC." (PMID 27974694, 2017). "Fifth, CXCR4 inhibitors can similarly enhance the sensitivity of cancer cells to certain chemo drugs." (PMID 28544785, 2017). "The present study was the first to observe the changes of SDF-1/CXCR4 axis in cancer cells with mifepristone treatment." (PMID 28938623, 2017). "Expression profiles of CXCL12 and CXCR4 are closely related to biological behaviors of cancer cells and the outcome of patients with GC." (PMID 28544785, 2017). "CXCR4 is a stromal cell derived factor-1 (SDF-1) receptor involved in cancer cell migration and invasion." (PMID 29069741, 2017). "The activation of CXCR4 and its cognate ligand stromal cell-derived factor-1 leads to the promotion of cancer cell proliferation and migration." (PMID 29117108, 2017). "PepR-NIR750 is a specific probe for non-invasive detection of human high CXCR4-expressing tumors and metastatic lesion and thus a valuable tool for cancer molecular imaging." (PMID 28566721, 2017). "Using the MTT assay, we tested a mechanistic link between mifeprsitone and suppression of cancer cells proliferation through the SDF-1/CXCR4 axis." (PMID 28938623, 2017). "A simultaneous and enhanced expression of CXCL12 and CXCR4 has been found in many cancers, such as breast, gastric, pancreatic, ovarian, cervical and oral squamous cell carcinoma." (PMID 29112161, 2017). "Affecting the CXCL12 signaling axis has potential for significant therapeutic benefit, as CXCR4 is over-expressed in more than 20 human cancers." (PMID 28055968, 2017). "Scatter plot of genes array data showed that LP-4 up-regulated the Igf1, Fam176a, Ulk-1, PERK, Cxcr4, and Sqstm1 (p62) genes in HeLa cancer cells." (PMID 28670281, 2017). "CXCR4 is expressed in a number of cancer cells, including prostate cancer, breast cancer and lung cancer." (PMID 28067275, 2017). "There are currently several CXCR4-targeting agents, including peptide antagonists and mAbs, being evaluated in combination with checkpoint blockade for cancer immunotherapy." (PMID 29212254, 2017). "The typical chemokine receptor CXCR4 is present in many cancers and is responsible for metastasis formation in several organs." (PMID 29156704, 2017).
cancer (continued). "An important target population for CXCL12-mediated recruitment and signaling are CXCR4+ cancer stem cells, which are mostly found in the invasive front and are essential for metastasis." (PMID 28423491, 2017). "Further experiments are ongoing in our laboratory to explore the possibility of a direct role of PATZ1 on the CXCR4 promoter in GBM as well as in other cancer-derived cell lines, where PATZ1 appears involved in counteracting EMT." (PMID 28938636, 2017). "The results demonstrated that human miR-125b, which positively regulates EMT and wnt/β-catenin signaling by targeting APC expression, is controlled by CXCL12/CXCR4 signaling in cancer cells." (PMID 28176874, 2017). "MMP-9 is a downstream signaling molecule of CXCR4 and is critical for cancer cell migration and invasion." (PMID 28969005, 2017). "The expression of CXCL12, the unique CXCR4 ligand, significantly increased in the collective invasion area where p16INK4A-immunopositive senescent cells were present, whereas CXCR4 was diffusely overexpressed in all cases of cancer tissues." (PMID 28489070, 2017). "CXCR4 is also notable for its involvement in the internalization of the HIV as well as in the progression of a wide range of cancers." (PMID 28261054, 2017). "The binding of CXCL12 to CXCR4 has been reported to play important roles in cancer growth, invasion and metastasis." (PMID 28489887, 2017). "We further report that CXCR4 contributes to the activation of the neuronal CaMKII/CREB pathway in cancer-induced bone pain." (PMID 28638088, 2017). "As such, studies have shown that CXCR4 increases the migration rate of several types of cancer cells." (PMID 28261054, 2017). "We developed LY2624587, a fully humanized CXCR4 mAb that is among the first-in-class anti-CXCR4 mAbs developed, for the treatment of patients with cancer." (PMID 29212254, 2017). "CXCR4 is overexpressed in a variety of human cancers including breast, lung, kidney, colon, ovarian, and brain." (PMID 28299514, 2017). "As part of a project to develop tools for quantifying CXCR4 on cancers non-invasively in humans, we re-examined CXCR4 expression on multiple cancers by immunohistochemistry (IHC) using a well validated antibody and staining protocol." (PMID 29088715, 2017). "Taken together, these findings demonstrated for the first time that CaMKII/CREB activation in spinal neurons is an important neuronal mechanism of CXCR4 signaling to pain sensitization in naive and cancer pain rats." (PMID 28638088, 2017). "In fact, there has been a great deal of recent interest in developing PET agents for visualizing CXCR4 expression on cancers." (PMID 29088715, 2017). "We have previously reported the production of 64Cu-plerixafor and studies in mice demonstrating the ability of this agent to image CXCR4-expressing tissues and cancers." (PMID 29088715, 2017). "Our group has found that CXCR4+ cancer cell migration in 2D is CXCL12 isoform-specific, but isoforms have not been examined and compared in 3D settings." (PMID 29117251, 2017). "Targeted metastasis of cancer cells with elevated expression of CXCR4 to specific sites guided by the high level of SDF-1 suggests a new therapeutic strategy to interrupt the SDF-1/CXCR4 axis and inhibit cancer metastasis." (PMID 28938623, 2017). "In the past, therapeutic strategies were proposed to target the SDF-1/CXCR4 axis of different cancers." (PMID 28196146, 2017). "Studies have shown that blocking the CXCR4 can reduce proliferation and metastasis, and induce apoptosis of cancer cell." (PMID 28489887, 2017). "During inflammation, the Cxcl12/Cxcr4 niche expands and supports cancer cell growth by paracrine release of growth factors such as Wnt5a." (PMID 29340033, 2017). "Dysfunction of the CXCL12/CXCR4 axis contributes to several human pathologies, including cancer and inflammatory diseases." (PMID 28410420, 2017). "Overexpression of miR-125b robustly triggered EMT and cancer invasion, which in turn enhanced the expression of CXCR4." (PMID 28176874, 2017).
cancer (continued). "Our results indicated marked inhibition of cancer cells attraction by inhibition of CXCR4 signalling." (PMID 28489070, 2017). "We uncovered a novel positive feedback circuit of CXCL12/CXCR4 axis and miR-125b in cancer invasion." (PMID 28176874, 2017). "Considering these factors, the CXCR4/CXCL12 axis is widely accepted as a potential therapeutic target for cancer therapy." (PMID 29263923, 2017). "SDF-1α and CXCR4 axis is important to signaling pathways in neovascularization including embryonic vasculogenesis and cancer." (PMID 28588623, 2017). "Studies examining expression of CXCR4 in cancer have used multiple antibodies, with some showing predominantly cytoplasmic and nuclear staining." (PMID 29088715, 2017). "The interaction between CXCL12 secreted by CAFs and CXCR4 expressed in cancer cells is also accountable for the direct growth effects elicited by activated stromal cells." (PMID 29240722, 2017). "Collectively, these results suggest that spinal CXCR4 promotes the up-regulated expression of NMDAR1 at the transcriptional level in cancer pain situations." (PMID 28638088, 2017). "CXCR4 activation stimulates the directed migration of cancer cells and increases their invasiveness." (PMID 28489070, 2017). "Treatment with a CXCR4 antagonist and/or CXCL16 neutralizing antibody, alone or in combination, significantly inhibited migration of cancer cells to brain metastatic cancer-associated fibroblast aggregates." (PMID 28649646, 2017). "The CXCR4+ cancer cells transduced with AAV-pCXCR4-LUC-RFP expressed both luciferase (LUC) and an RFP reporter." (PMID 27835894, 2016). "Since several studies have reported ROS-mediated regulation of CXCR4 in human cancers, we determined the intracellular level of ROS in MCL cells using FACS." (PMID 26885608, 2016). "CXCR4 plays important roles in immune trafficking and in the migration of cells including neurons, germ cells, cancer cells, and other cell types." (PMID 27070582, 2016). "Stem cell surface CXCR-4 binds with SDF-1α secreted by cancer cells, which stimulates stem cells to express more CXCR-4." (PMID 27494901, 2016). "CXCR4 is believed to be a key factor in the cross-talk between cancer cells and their microenvironment, which makes CXCR4 a very promising prognostic biomarker and target for cancer therapy." (PMID 27517626, 2016). "Use of pharmacological inhibitors and blocking mAbs showed that both CXCR2 and CXCR4 are predominantly involved in the migration of the other cancer models towards Ad-CM." (PMID 26756352, 2016). "He showed that small molecular inhibitors of CCX451, CCX751 and CXCL11 compete with SDF1a binding to CXCR4, with human cancer cell lines showing a contradictory pattern of CXCR4 expression and SDF1a binding." (PMID 27092040, 2016). "Experimental metastatic mouse models have provided evidence that targeting CXCR4 impairs cancer cell metastasis." (PMID 26920352, 2016). "Both mechanisms belong to underlying principles of cancer progression and are partly driven by the homeostatic chemokine CXCL12 and its receptor CXCR4." (PMID 27835905, 2016). "The overexpression of CXCR4 in cancers and its importance in normal biological functions promotes the need for identification of tumors most likely to be responsive in order to achieve better therapeutic outcomes." (PMID 26848769, 2016). "Among them, CXC ligand 12 (CXCL12, also called stromal-derived factor-1), one of CXC chemokines, was previously shown to have important impacts on proliferation and invasion of many types of cancer cells, via its specific receptor, CXCR4." (PMID 27542220, 2016). "Among chemokine receptors, CXCR2 mRNA expression was decreased by 12-fold and CXCR4 mRNA expression was upregulated nearly 7-fold throughout cancer progression." (PMID 27143385, 2016).
cancer (continued). "Recent studies have drawn much attention to CXCR4-high cancer cell metastasis to CXCL12-rich tissues suggesting that such cancer cells have hijacked the CXCL12- guided mechanism of cell homing to establish metastasis." (PMID 26993780, 2016). "A number of investigations on cancer cells report a correlation of NF-κB increased levels and CXCR4." (PMID 27594840, 2016). "Another important feature is that treatment with cannabinoids has been shown to reduce invasiveness of cancer cells as well as CXCR4-mediated migration of immune cells." (PMID 27769052, 2016). "In light of this, the CXCL12-CXCR4 axis is of great therapeutic interest and pharmacologic approaches are being developed to target CXCR4 signaling as an anti-cancer strategy." (PMID 27528222, 2016). "A series of studies reported the role of CXCR4 in modulation of cancer cells migration in several human malignancies, especially due to increase production of MMPs." (PMID 27871286, 2016). "Stromal cell derived factor 1 alpha (SDF-1α) and its receptor, CSC chemokine receptor 4 (CXCR4), have been identified as key molecules responsible for the tropism of stem cells in many cancers." (PMID 27494901, 2016). "Our previous study indicated that CD133 + CXCR4+ cancer cells are possible migratory CSCs subtypes in colon cancer." (PMID 26864651, 2016). "The mammary fat pad and bone microenvironment have been shown to induce CXCR4 gene expression in cancer cells." (PMID 27809841, 2016). "The chemokine CXCL12 and its corresponding receptor CXCR4 are key players in the development of several cancers." (PMID 27439769, 2016). "Due to the superior pharmacokinetic profile and exquisite selectivity of monoclonal antibody, LY2624587 provides an alternative approach for evaluation of CXCR4 inhibition in treatment of cancer or other diseases." (PMID 26954567, 2016). "Drug and gene delivery systems based on nanomaterials are thus designed to target against CXCR4 and facilitate cancer therapy and imaging." (PMID 27173676, 2016). "It has been demonstrated that CXCL12 and CXCR7, another high affinity receptor of CXCL12, except for CXCR4, play pivotal roles in growth, migration, chemotaxis, adhesion and spreading of cancers." (PMID 27542220, 2016). "Several studies by other groups have demonstrated that the expression of CXCR4 or CXCL12 in cancer cells worsens the prognosis in patients with ESCC." (PMID 27439769, 2016). "The CXCL12/CXCR4 axis has been involved in homing of breast and prostate cancer cells to bone where cancer cells have aberrant expression of CXCR4, the receptor for the CXCL12 chemokine." (PMID 27809841, 2016). "For example, cancer cells, such as hematopoietic stem cells (HSCs), are capable of expressing C-X-C motif chemokine receptor 4 (CXCR4) and thus take advantage of the same physiological mechanism of chemoattraction used by HSCs." (PMID 27556456, 2016). "Stromal cell-derived factor-1 (SDF-1) and its receptor, C-X-C chemokine receptor type 4 (CXCR4), are key regulators for cancer metastasis." (PMID 27835898, 2016). "Chemokine receptors are being studied currently as therapeutic targets and CXCR4 is the most widely expressed chemokine receptor on cancer cells including breast, prostrate, pancreatic, kidney and brain cancer cells." (PMID 27863376, 2016). "The CXCR4/CXCL12 signaling axis is known to be involved in the metastasis of cancer cells and CXCR4 chemokine receptors are highly expressed in various tumors compared to normal cells." (PMID 27445824, 2016). "LY2624587, along with MDX-1338, are among the first in class anti-CXCR4 monoclonal antibody developed for cancer." (PMID 26954567, 2016). "Although the relationship between CXCL12/CXCR4 expression levels and cell behaviour was described in a variety of malignant tumors, few have assessed this relationship for esophageal cancer." (PMID 27439769, 2016). "BITC suppressed apoptosis and cancer cells metastasis by activating caspase-3 activity and restraining CXCR4 and MMP2/9 expression." (PMID 27716619, 2016).
cancer (continued). "Activation of the CXCL12–CXCR4 axis recruits not only CXCR4+ cancer cells but also CXCR4+ BMDC that promote angiogenesis in a vascular endothelial growth factor (VEGF)-dependent or -independent manner." (PMID 27136535, 2016). "Clinically, expression of CXCR4 protein in tumors is used to predict cancer aggressiveness, survival probability and metastasis-associated mortality." (PMID 27769052, 2016). "AMD3100 is not toxic to host cells at concentrations up to 500 mM and the CXCL12/CXCR4 blockade efficiently decreases cancer cell proliferation." (PMID 27439769, 2016). "It further shows significance of this axis for maintenance of aggressive phenotype and also signifies of studying chemokines other than CXCR4 in cancer progression to define the disease process and develop better therapeutic interventions." (PMID 26799186, 2016). "One of the most important GPCRs in cancer migration and invasion is CXCR4, however, the correlation between CXCR4 and USP33 hasn't been investigated." (PMID 27835898, 2016). "Binding of CXCR4 to CXCL12 is also proposed to play a role in cancer metastases, and CXCR4 antagonists are under study in human clinical trials for solid and non-solid tumors." (PMID 27005825, 2016). "In order to avoid unwanted cancer cell survival resulted from CXCR4 upregulation after LDE225, the drugs that inhibit CXCR4 or autophagy such as AMD3100 or 3-MA can be an effective adjuvant to enhance the cytotoxicity of LDE225." (PMID 26885608, 2016). "CXCR4 inhibitors are currently in clinical trials as anti-cancer therapeutics (e.g. ALX-0651 [NCT01374503], MSX-122 [NCT00591682], BMS-936564 [NCT02305563, NCT01359657, NCT01120457, NCT02472977])." (PMID 26848769, 2016). "Transcriptional regulation of the CXCR4 gene is a key determinant of net cell surface expression of CXCR4 and its subsequent function in transformed epithelial cells and cancer cells." (PMID 27809841, 2016). "CXCR4 is highly expressed in various cancer types and is considered as the most widely expressed cancer-associated chemokine receptor." (PMID 27517626, 2016). "CXCR4 has been found to be a prognostic marker in various types of cancer and plays a role in the cell proliferation and migration of cancer cells." (PMID 27293448, 2016). "Suppression of CXCR4 and its signaling axis is therefore a common strategy to inhibit cancer cell migration and metastasis." (PMID 27173676, 2016). "With the rapid increase in our knowledge of non-HIV-related functions of CXCR4, other potential applications for treatment of cancer have emerged and have gradually replaced the original intent to use CXCR4 antagonists as anti-HIV drugs." (PMID 27175473, 2016). "Aside from the inflammation-induced expression of CXCR4 by TNF,21,24 CXCR4 (over)expression is associated with the extent and site of metastases as well as with poor prognosis in more than 23 types of cancer." (PMID 28255525, 2016). "Altogether, we have described a fully humanized CXCR4 monoclonal antibody that was advanced into the clinic for treatment of cancer." (PMID 26954567, 2016). "Cancer cells expressing CXCR4 form distant metastases in secondary organs that produce high levels of CXCL12, in human specimens and murine models." (PMID 26744352, 2016). "According to the current body of knowledge, CXCR4 is involved in various cancer-related processes, including its development and metastasis." (PMID 26622806, 2015). "Currently AMD3100 (plerixafor, Mozobil) is an FDA approved CXCR4 antagonist that is being tested as a cancer therapeutic." (PMID 25775124, 2015). "C-X-C chemokine receptor 4 (CXCR4) is frequently over-expressed in various types of cancer; many agents against CXCR4 are in clinical development currently despite variable data for the prognostic impact of CXCR4 expression." (PMID 25669980, 2015).